ZFAND5 (zinc finger AN1-type containing 5)
Description:
Involved in protein degradation via the ubiquitin-proteasome system. May act by anchoring ubiquitinated proteins to the proteasome. Plays a role in ubiquitin-mediated protein degradation during muscle atrophy. Plays a role in the regulation of NF-kappa-B activation and apoptosis. Inhibits NF-kappa-B activation triggered by overexpression of RIPK1 and TRAF6 but not of RELA. Also inhibits tumor necrosis factor (TNF), IL-1 and TLR4-induced NF-kappa-B activation in a dose-dependent manner. Overexpression sensitizes cells to TNF-induced apoptosis. Is a potent inhibitory factor for osteoclast differentiation.
Synonyms: ZA20D2; ZNF216; ZFAND5A
Tractability: Small molecule: a structure with a bound ligand is known. PROTAC: ubiquitination databases record sites on it.
Gene: Protein-coding gene on chromosome 9 (72,351,412 to 72,365,328, reverse strand). Ensembl gene ENSG00000107372.
Subcellular location: Cytoplasm
Subcellular location (Human Protein Atlas): Nucleoplasm; Cytosol; Nuclear bodies
Gene Ontology:
Molecular function: protein binding; DNA binding; zinc ion binding
Cellular component: cytoplasm
Genetic constraint (gnomAD): Loss-of-function variants: 4 observed, 22.13 expected, observed/expected ratio (o/e) 0.18, 90% interval 0.088 to 0.41. The upper end of that interval is the gene's LOEUF score, 0.41, which puts it in group 1 of 6, group 1 being the genes least tolerant of losing a copy. Missense variants: 154 observed, 251.32 expected, observed/expected ratio (o/e) 0.61, 90% interval 0.54 to 0.7. Synonymous variants: 68 observed, 80.96 expected, observed/expected ratio (o/e) 0.84, 90% interval 0.69 to 1.03.
Homologues: Orthologues: chimpanzee ZFAND5 (100% identical), dog ZFAND5 (100% identical), guinea pig ZFAND5 (100% identical), macaque ZFAND5 (100% identical), pig ZFAND5 (99% identical), rabbit ZFAND5 (99% identical), mouse Zfand5 (99% identical), rat Zfand5 (98% identical), tropical clawed frog zfand5 (88% identical), Drosophila melanogaster drn (38% identical), Caenorhabditis elegans mstr-1 (37% identical), Drosophila melanogaster CG43675 (28% identical), and 1 more. Paralogues in human: ZFAND6 (56% identical), ZFAND3 (26% identical).
Diseases named in the same sentence as ZFAND5 in open-access papers:
ZFAND5 is named in the same sentence as 19 diseases in open-access papers, as found by Europe PMC text mining. Sharing a sentence is not in itself a finding about the gene and the disease. The quoted sentences say what the papers report.
colon cancer (2 papers, 2022 to 2023). "However, other studies showed that ZFAND5 was highly expressed in more aggressive nasopharyngeal carcinoma cells, and ZFAND5 may be associated with proliferation of colon cancer, indicating that ZFAND5 may have pro-tumor effects." (PMID 35912230, 2022). "LPS also increased COX2, CXCL1, ELK1, ICAM1, TNFSF10 and ZFAND5 but decreased BCL2L1, CYP19A1 and E2F1 mRNA levels in the colon cancer cells." (PMID 37705049, 2023). "qPCR showed that LPS increased CXCL1, ELK1, ICAM1 and ZFAND5 mRNA levels, but decreased BCL2L1 and E2F1 mRNA levels in the colon cancer cells." (PMID 37705049, 2023).
Alzheimer disease (1 paper, 2022). A progressive, neurodegenerative disease characterized by loss of function and death of nerve cells in several areas of the brain leading to loss of cognitive function such as memory and language. "Gene-based analyses implicated AGXT2 and CALN1 for VL, while analyses of protein-protein interactions implicated synaptic proteins previously associated with Alzheimer disease biology, SYT9 and NRXN1 for VSTM; ZFAND5, GRIK2, and ZC3H18 for VL; and PRLHR for paragraph recall." (PMID 35974141, 2022).
bipolar disorder (1 paper, 2023). A disorder of the brain that causes unusual shifts in mood, energy, activity levels and the ability to carry out day-to-day tasks. "Potential candidate genes for bipolar disorder with metabolic syndrome were found in 5 candidate genes (AP1G2, C1orf54, DMAC2L, RABEPK and ZFAND5), all of which have diagnostic significance." (PMID 37860165, 2023).
knee osteoarthritis (1 paper, 2024). "Specifically, cinnamaldehyde may affect knee osteoarthritis by regulating apoptosis-related genes such as ZFAND5, BCL6, ELL2, FOSL2, MARCKS, and SGCD." (PMID 39376659, 2024).
osteoarthritis (1 paper, 2024). A noninflammatory degenerative joint disease occurring chiefly in older persons, characterized by degeneration of the articular cartilage, hypertrophy of bone at the margins and changes in the synovial membrane. "Firstly, the identified APDEGs—MARCKS, ZFAND5, BCL6, FOSL2, ELL2, and SGCD—may provide deeper insights into osteoarthritis pathogenesis." (PMID 39376659, 2024).
tumor (3 papers, 2016 to 2022). "Taken together, the current knowledge of ZFAND5 role in tumor progression is very poor and controversial." (PMID 35912230, 2022). "Given that ZFAND5 affects cytokine expression and is involved in immunology, it would be a very interesting topic to further study the role of ZFAND5 in tumor response to immune checkpoint inhibitors." (PMID 35912230, 2022). "High expression of ZFAND5 appeared to be correlated with larger tumor size, though the statistical significance was not remarkable(P=0.155)." (PMID 35912230, 2022).
cancer (2 papers, 2016 to 2022). A tumor composed of atypical neoplastic, often pleomorphic cells that invade other tissues. "The function of ZFAND5 in cancer progression is rarely investigated." (PMID 35912230, 2022). "However, the function of ZFAND5 in cancer progression is rarely investigated, and the role of ZFAND5 in pCCA is never yielded." (PMID 35912230, 2022).
neurological disorders (1 paper, 2021). "They include characteristic genes, Prnp, Cct4, Vegfd (Figf), Map9 (Mtap9), Pik3cg, Zfand5, Endog, and Hbq1, which are reportedly associated with AD, CJD, and/or related neurological disorders." (PMID 34959983, 2021).
ZFAND5 also shares sentences with these, for which no sentence is quoted: Stroke (2 papers); breast carcinoma (1); esophageal disorder (1); medulloblastoma (1); melanoma (1); metabolic syndrome (1); multiple myeloma (1); nasopharyngeal carcinoma (1); oral squamous cell carcinoma (1); Perihilar Cholangiocarcinoma (1); prostate carcinoma (1).